CX3CR1 (C-X3-C motif chemokine receptor 1)
Diseases named in the same sentence as CX3CR1 in open-access papers (continued):
Sharing a sentence is not in itself a finding about the gene and the disease.
infection (continued). "We next quantified viable Mtb bacilli in the lungs of Het, Ccr2 and Cx3cr1 single knockouts, and DKO mice at 4 weeks post-infection." (PMID 40497732, 2025). "We identified ten NK subgroup-specific marker molecules (Kcnj8, Cmah, Ccnd2, Cx3cr1, Thy1, Tnfrsf9, Zbtb20, Gng11, CD226, Egr3) from C0 to C9 and assessed their expression changes during infection using RT-qPCR." (PMID 40244063, 2025). "The cDC2 population included a small subpopulation of CX3CR1+PDPN+ cells, with a small statistically significant decrease from day 2 post-infection to day 23 post-infection." (PMID 39355243, 2024). "Both CXCR6+ CD8 T cells and CX3CR1+ CD8 T cells from the liver and spleen after resolved infection efficiently eliminated target cells and produced interferon-γ (IFNγ) and tumour necrosis factor (TNF) ex vivo after cognate stimulation." (PMID 38987588, 2024). "In hepatic antigen-specific CD8 T cells after resolved infection, phenotypic profiling showed mutually exclusive expression of the chemokine receptors CXCR6 and CX3CR1, whereas in spleen only CX3CR1+ cells were detected." (PMID 38987588, 2024). "The G protein binds to the CX3C chemokine receptor, CX3CR1, through the CX3C motif, thus facilitating the infection of primary human airway epithelial cells." (PMID 39220282, 2024). "The combination of CX3CR1 and PDPN in the myeloid population revealed that the F4/80+ macrophage population showed a significant increase in these two markers throughout the infection phases." (PMID 39355243, 2024). "The increase in the CX3CR1+PDPN+ F4/80+ macrophage population had statistically significant peaks at day 2, 5 and 16 post LucAdv5 infection." (PMID 39355243, 2024). "The incoming monocytes showed a significantly high expression of both CX3CR1 and PDPN on day 2 post-infection." (PMID 39355243, 2024). "Indeed, we found that depletion of CX3CR1+ cells in the brain at late time points post-infection (which may include inflammatory border macrophages in addition to microglia) continued to reduce brain fungal burden, whereas this effect was absent in our other models." (PMID 37938547, 2023). "For example, experimental infection with HIV induces the overexpression of both FKN and CX3CR1 in neurons and microglia, respectively but also the expression of CX3CR1 in astrocytes." (PMID 36644710, 2023). "This infection is TLR4- and CX3CR1-dependent and polarizes the differentiation of neonatal macrophages toward an M2-like phenotype." (PMID 37896776, 2023). "For example, TEM cell subsets expressing high levels of CX3CR1 (Sp cluster 1, 11) were equally present in MCMV-GP33 infected and co-infected mice and more abundant as compared with infection with LCMV Armstrong (cluster 4 and 5)." (PMID 33458613, 2021). "In Mtb-infected mice, CXCR3+KLRG1−Tbetdim T cells migrate into the lung parenchyma and control the infection, while intravascular (iv) T cells have a high expression of KLRG1, CX3CR1, and T-bet." (PMID 33879592, 2021). "Peripheral monocytes, which are recruited to the site of infection, produce TGF-β and differentiate into monocyte-derived CX3CR1+ macrophages, which become alternatively activated due to IL-4/IL-13 signaling via IL-4Rα." (PMID 33829283, 2021). "From dpi 4, the total microglia population upregulated CD45, increased their granularity (side scatter - SSC-A) and progressively downregulated CX3CR1, F4/80 and CD68 over the course of infection." (PMID 34311763, 2021). "In summary, Ifit2 plays a role in maintaining CX3CR1 surface expression in both CD45hi CD11b+ monocyte derived macrophages and CD45lo/int CD11b+ CNS resident microglia following MHV-RSA59 infection." (PMID 33253295, 2020). "Most of the genes for chemokines/chemokine receptors (CCR2, CCR6, CCR7, CSF2RB, CX3CR1 and CXCR4) and cytokines/cytokines receptors (IL1R2, IL8, IL18, IL20RA and IL22RA2) were down-regulated after infection by vvIBDV at 3 dpi." (PMID 33110122, 2020).
infection (continued). "We show that F4/80+, CD11b+, CD11cint, CX3CR1+, MHC class II+, Ly6C−, ARG1+, and NOS2+ macrophages accumulate in the small intestine during infections in mice." (PMID 31455692, 2019). "To study the mechanisms of microglia recruitment to sites of infection, we first established co-cultures of neurons and GFP-positive microglia from Cx3Cr1+/GFP mice and performed time-lapse imaging over a 48 h period." (PMID 30027450, 2018). "It has often been difficult to identify precisely the cell responsible for producing IL-23 in infection or inflammation, in great part because Mφs and DCs share many phenotypic features such as CD11c, MHCII, CX3CR1, and CD11b." (PMID 29203542, 2018). "Recent studies have shown that CX3CR1+ monocytes can regulate learning and learning-dependent dendritic spine remodeling via TNF-α following infection with poly (I:C), a synthetic analog of double-stranded RNA." (PMID 28848542, 2017). "A significant reduction in CX3CR1+ IL10-producing macrophages, the in vivo analog of the Mreg species, at three weeks post infection was observed, resulting in a decrease to 50% of wild-type levels in LANCL2-/- mice." (PMID 27936058, 2016). "Our current working model is that initial 2–20 G interactions with CX3CR1, GAGs, and/or other factors mediates attachment that likely precedes F-EGFR interaction, EGFR activation, and infection." (PMID 27152417, 2016). "The phenotype of intrahepatic CD11b+ myeloid cells during parasite-induced liver inflammation was investigated in CX3CR1-GFP+/- C57BL/6 mice infected with T. congolense at day 7, 14 and 21 post infection (pi)." (PMID 26020782, 2015). "Even >200 days after AdOVA infection, antigen-specific GFP+ (CX3CR1+) and GFPneg (CX3CR1neg) memory CD8+ T cells were found arguing that both memory T-cell populations are long lived." (PMID 26404698, 2015). "After clearance of infection, only long-lived memory CD8+ T cells with immediate cytotoxic effector function expressed CX3CR1." (PMID 26404698, 2015). "Virus-specific CX3CR1+ memory CD8+ T cells are scarce during chronic infection in humans and mice but increase when infection is controlled spontaneously or by therapeutic intervention." (PMID 26404698, 2015). "A mAb against CX3CR1 significantly reduced RSV infection compared to an isotype control, indicating that the increase in infection was due to RSV interaction with the receptor." (PMID 26658574, 2015). "At 60 d.p.i. of CX3CR1+/GFP reporter mice, the majority of CD8+ T cells in the blood and spleen, which were specific for OVA (after AdOVA or L.m.-OVA infection) or LCMV-gp33, showed GFP (CX3CR1) expression." (PMID 26404698, 2015). "If CX3CR1 is a receptor for the RSV G protein on HAE cultures, the G protein CX3C motif would likely be important for infection of these cells." (PMID 26658574, 2015). "To determine if the accumulation of PD-L2+ AAM from CX3CR1-GFP+ monocytes was CD4+ T cell dependent, we depleted CD4+ T cells from 5.5 to 6.5 weeks post-infection and analyzed PD-L2 expression on CX3CR1-GFP+ cells from the liver." (PMID 24967715, 2014). "CX3CR1-GFP+ monocytes and macrophages accumulated around eggs and in granulomas during infection and upregulated PD-L2 expression, indicating differentiation into AAM." (PMID 24967715, 2014). "Since these cells exclusively express CX3CR1 in the healthy CNS, and its ligand CX3CL1 is constitutively expressed by neurons, this receptor:ligand interaction is likely to function during infection." (PMID 25324719, 2014). "We gated on CD45+ (Blood) Ly6Chigh CX3CR1-GFP+ monocytes, as well as CD45+ (Blood) Ly6Clow CX3CR1-GFP+ monocytes, to examine PD-L2 expression on these cells at 6 weeks post-infection, when PD-L2+ cells can be found in the blood." (PMID 24967715, 2014). "Some others such as CCL3, CCR5, CXCL9, CXCL10, CX3CR1 and CCL24 showed a low expression during the infection." (PMID 22905138, 2012).
infection (continued). "The chemokine receptors involved in NK cell migration to the site of infection have been assessed for a few pathogens, and from these studies it appeared that CCR2, CCR5, CXCR3 and CX3CR1 play a key role in NK cells migration during infection." (PMID 23272202, 2012). "Furthermore, soluble G protein (sG) can bind to CX3CR1 and competitively interfere with cell signaling induced by the chemokine CX3CL1, resulting in inhibition of immune cell recruitment to the site of infection." (PMID 42043252, 2026). "MLN Mtb burden was lower than at 4 weeks post-infection, as expected, but was not affected by CCR2 or CX3CR1 deficiency at the earlier time point." (PMID 40497732, 2025). "CX3CR1 expression marks the most differentiated Th1 effector population and functionally serves as a tissue homing receptor toward the ligand CX3CL1 (fractalkine) produced at sites of infection." (PMID 40433376, 2025). "Nevertheless, IFN-γ signaling on Cx3cr1+ cells was not required to promote IL-18 release during infection." (PMID 39446964, 2024). "Imaging flow cytometry and RSV attachment assay showed that CX3CR1, expressed on airway ciliated cells, interacts with RSV G protein, facilitating virus attachment and the infection of human airway epithelial cells, and modulates cell responses to infection." (PMID 38674036, 2024). "Finally, in a model of infection with Salmonella, resident macrophages expressing CXCL13 and CX3CR1 promote the infiltration of B and CD4+ T cells in areas of infection, where they are activated, giving rise to TLS induction." (PMID 37622111, 2023). "CX3CR1 is expressed on various cell types, including innate and adaptive immune cells, and on motile cilia of AECs, which matches the RSV cell tropism during an infection." (PMID 37896776, 2023). "The studies presented here show that TCR engagement of activated CD8+ T cells in a secondary site of infection correlated with profound transcriptional changes and expression of markers of effector T cells (for example co-expression of KLRG1 and CX3CR1 and cytokine production)." (PMID 35727849, 2022). "While basal expression of these receptors and integrins was comparable in all groups of uninfected mice, CCR9 and CX3CR1 were significantly upregulated on pDC after infection in WT but not in Tlr7−/y mice." (PMID 36278864, 2022). "What is more, CX3CR1+ memory T cell plays a major killing role in secondary infection, while CX3CR1− memory T cell has almost no cytotoxicity." (PMID 35528178, 2022). "At 10 dpi, the splenic OT-I were a heterogenous population based on KLRG1 and CX3CR1 but by 6 weeks post infection, when these cells did not express Nur77-GFP there was a more homogeneous (>98%) population of OT-I that maintained a KLRG1+CX3CR1+ phenotype." (PMID 35727849, 2022). "At the early time point post infection, we focused on the total myeloid-derived (CD45+CD11b+), neutrophil (CD45+CD11b+F4/80-Ly6G+Ly6CloCX3CR1-) and macrophage (CD45+CD11b+F4/80+Ly6G-Ly6C+CD115+CX3CR1+) populating the cornea of WT and OPN KO mice." (PMID 36685562, 2022). "Notably, we found that the expression of specific markers of M1 type microglia (Aif1, Cd86, Cd40, Ccl2, Ccr2, Cx3cr1, IL-1β, IL-6, and NOS2) was elevated post infection." (PMID 36618398, 2022). "In these mice, wild-type MCMV titers were reduced in the salivary gland after f.p. infection, but not intraperitoneal (i.p.)infection, suggesting that CX3CR1+ patrolling monocytes were important for dissemination from the foot pad." (PMID 33508041, 2021). "TEM cell subsets, however, were mainly responsible for the difference between LCMV Armstrong and MCMV-GP33 infections, with Ly6C+KLRG1−CD127+ cells being more abundant in LCMV Armstrong and KLRG1+CX3CR1+NKG2A+ GP33-specific CD8+ TEM cells defining the phenotype after MCMV-GP33 infection." (PMID 33458613, 2021).
infection (continued). "For instance, we observed a pattern of expression of the chemokine receptor Cx3cr1 that straddles the Tpex and Tex subtypes in the TIL atlas, as well as a gradient of expression for this molecule within the Tex compartment in infection." (PMID 34017005, 2021). "Next, we generated mice lacking EZH2 in the macrophage lineage, for in vivo infection studies, by using the CX3CR1‐cre driver line." (PMID 34464475, 2021). "During infection with E. histolytica, mice showed differential expression of CD86 and CX3CR1." (PMID 32651360, 2020). "However, infection resulted in NK cells and ILC1-like cells gaining expression of CCR8 and CX3CR1 compared to NK cells and ILC1s in uninfected mice." (PMID 31393266, 2019). "In the mouse model, blocking G binding to CX3CR1 decreases disease with infection by a mechanism not dependent on a decrease in infection but through an anti-inflammatory-like effect." (PMID 31330970, 2019). "The CX3CR1 and HSPG binding sites are distinct but spatially close; therefore, HSPG mimetics may inhibit CX3CR1-mediated infection via steric hindrance." (PMID 31266258, 2019). "In contrast, the number of CD45loCD11b+CX3CR1+Ly6C− microglial cells increased with age, but no additional infection-induced increase was observed." (PMID 30323282, 2018). "It should be noted that when wild type mice were infected with mutant MCMV lacking MCK2, CX3CR1+ inflammatory monocytes were recruited to the infection site." (PMID 30037007, 2018). "Expression of CX3CR1 on virus-specific CD8+ T cells appeared shortly after clearance of experimental infection, then steadily increased to reach a plateau 2 weeks and was still found up to 200 days after infection." (PMID 26404698, 2015). "In this experiment, rgRSV retained some of its infectivity for CX3CR1-/- mice, suggesting that RSV also uses an alternate, less efficient mechanism for initiating infection in the absence of the G protein-CX3CR1 interaction." (PMID 26658574, 2015). "Mice that after DTx treatment specifically lacked il23a in their CX3CR1+ cell compartment died by day 10–12 after infection." (PMID 25761673, 2015). "This led us to analyse GFP (CX3CR1) expression in CD62LhiCD127+KLRG1neg TCM, CD62LlowCD127+KLRG1neg TEM and KLRG1+CD8+ T cells derived from naïve OT-ICX3CR1-GFP T cells at 60 days after AdOVA infection." (PMID 26404698, 2015). "Because mAb 131-2g blocks G protein binding to CX3CR1, our finding that mAb 131-2g neutralizes infection of clinical isolates for HAE cultures indicates that the use of CX3CR1 is not an artifact of using a laboratory strain of RSV." (PMID 26658574, 2015). "The frequency of cells that were in S phase was the same between uninfected mice and mice at 6 weeks post-infection, indicating the CX3CR1-GFP+ cells are not proliferating more at this time point during infection." (PMID 24967715, 2014). "CD4+ T cells represent approximately 10% of the CX3CR1-GFP+ population at 7 weeks post-infection (data not shown)." (PMID 24967715, 2014). "It is likely that infection-induced production of inflammatory cytokines, such as TNF-α, IL-1, and IFN-γ, may stimulate CX3CR1 production in HAEC." (PMID 24851083, 2014). "Based on the expression pattern of these molecules, we analyzed the frequency of human CD8+ T cells expressing CX3CR1 and/or CXCR1 from the spleens of HIV-1-infected and uninfected hNOK/B51Tg mice and of HIV-1-infected and uninfected hNOK mice at 6 weeks post-infection." (PMID 22880104, 2012). "Our data showed a totally reduced expression of CX3CR1 on HSCs during all infection stages and the expression was not significantly changed after PZQ treatment." (PMID 22905138, 2012). "However, the interaction between the CX3C-motif of the RSV G protein and CX3CR1 is not the only mechanism mediating the infection of airway epithelial cells and subsequent cellular signaling." (PMID 40295855, 2024).
infection (continued). "Considering the increase in cx3cr1 expression found in our study and the regulation of CXCL1 regulation by SCFAs23, we hypothesize that SCFA feeding shaped the generation and migration of patrolling monocytes to the liver during the infection." (PMID 37865711, 2023). "However, mean cell velocity in both macrophages and CX3CR1 cells did not significantly increase correlated to increased contact ratio at 5 h post-infection." (PMID 33520993, 2020). "However, it has been shown that that global deletion of CX3CR1-expressing cells from day 3 of a PbA infection did not substantially affect the course of ECM14." (PMID 27991544, 2016). "Furthermore, specific depletion of CX3CR1 expressing cells, including perivascular and meningeal macrophages and microglia, from day 3 of infection utilizing CX3CR1-iDTR mice also failed to inhibit development of ECM." (PMID 26562533, 2015). "To further demonstrate the role of Cx3cr1 in hepatic granuloma formation induced by S. japonicum eggs, we then examined hepatic Cx3cr1 expression in WT mice 8 weeks after cercariae infection; age matched WT mice in the absence of S. japonicum infection served as controls." (PMID 26035381, 2015). "Accordingly, CX3CR1+ CD8+ cells are a major component of the cytotoxic response to RSV infection, and that infection with an RSV mutant lacking the G gene dramatically increases the number of CX3CR1+ T cells in the lungs and reduces Th2-type cytokine expression." (PMID 24040360, 2013). "However, it was again not clear that they were required, as the kinetics of initial infection of the salivary gland were identical in the presence or absence of CX3CR1+ patrolling monocytes and only the amplification of MCMV within the salivary gland was impaired in the absence of CX3CR1." (PMID 33508041, 2021). "It is hypothesized that MCK2 functions through the chemokine receptor CX3CR1 as infection of mice lacking CX3CR1 on monocytes, dendritic cells, and NK cells had greatly reduced viral dissemination to the salivary gland while primary dissemination was not impacted." (PMID 30037007, 2018). "Importantly, treatment significantly reduced both the frequency and absolute number of Ly6C+CCR2+CX3CR1+/- inflammatory or Ly6C+CCR2-CX3CR1+ inflammatory monocyte derived cells in LmLm mice, demonstrating that IFN-γ drives a proportion of monocyte recruitment during secondary infection." (PMID 28666021, 2017). "Independent of the vaccination/infection regimen, we observed that the S-specific CD8 T cells adapted effector-memory-like phenotype (CX3CR1+KLRG+), expressing tissue-residential markers (CD62L−CD44+)." (PMID 41035684, 2025). "Detailed analysis of microglial dynamics using CX3CR1-GFP mice revealed that T. gondii-infected microglia remained stationary, and infection did not increase the extension/retraction of microglial processes." (PMID 36445695, 2022). "Incubation of HAE cultures with anti-CX3CR1 before, during and after inoculation inhibited RSV infection to a greater extent, but again did not reduced infection of HeLa cultures." (PMID 26658574, 2015). "At 60 days after AdOVA infection in mice, GzmB expression was exclusively found in GFP+ (CX3CR1+) memory OT-ICX3CR1-GFP T cells irrespective of their CD62L expression level." (PMID 26404698, 2015). "To define at which time point upon infection Tex subset composition is altered in the absence of HDAC1, we examined the kinetics of the appearance of CX3CR1+ cells at 48 and 67 h as well as day 5 and 8 p.i. and also determined the activation and expansion of early Tex cells." (PMID 40464916, 2025). "In their study, they detected virus-specific CX3CR1+ GzmB+ CD8+ T cells in patients with chronic viral infections, which suggested that continuous antiviral immunity was present, but without resolution of the infection." (PMID 33525328, 2021). "Thus, although >90% of macrophages in the SI LP express high levels of CX3CR1, these cells are absent from lymph after STM infection." (PMID 30487173, 2019).